NPR1 (natriuretic peptide receptor 1)
Diseases named in the same sentence as NPR1 in open-access papers (continued):
Sharing a sentence is not in itself a finding about the gene and the disease.
infection (continued). "When there is no pathogen infection, NPR1 is continuously cleared by proteasomes to limit the activity of its coactivator, thereby preventing untimely SAR activation." (PMID 36555841, 2022). "Mutation of NPR1, but not ICS1/SID2, was reported to adversely affect dual phosphorylation of MPK3 and MPK6 in Arabidopsis after infection with P. syringae or flg22 treatment." (PMID 36523630, 2022). "Our observations for the behavior of the elements of the SAR feedback loop for signal amplification after infection in Col-0 correspond to the literature, although increases in NPR1 expression were not significant." (PMID 36292941, 2022). "Without a Vd991 infection, the expression levels of NPR1, PR1 and PR5 in roots did not significantly change when exposed to ACC treatments." (PMID 35918649, 2022). "During infection with virulent or attenuated strains, the loss of ALD1 does not increase the susceptibility of npr1 or sid2 mutants, suggesting the main role of ALD1 in this context is in amplifying the SA-related module." (PMID 36523630, 2022). "The pathogen infection-induced dynamic accumulation of ABA mediates the degradation of non-expresser of PR genes 1 (NPR1) through the CUL3NPR3NPR4 proteasome pathway." (PMID 35336696, 2022). "After infection, however, BAK1 proteins accumulated to the WT level in npr1 and sid2 mutants, and BAK1 levels in the double mutants could not be distinguished from npr1 and sid2 mutants." (PMID 36523630, 2022). "Additionally, macroscopic HR-associated leaf collapse still occurs in these mutants, although NPR1 and ICS1/SID2 somewhat affect the development of HR symptoms after infection with avirulent strains of P. syringae (> OD600 = 0.01)." (PMID 36523630, 2022). "The DEA of NPR proteins indicated that 4 PM-responsive and 4 DM-responsive NPR (comprised of NPR1 and NPR2) genes were expressed differentially during infection and all NPR genes were shown to be steadily up-regulated from initial to later stages of both powdery and downy mildew infection." (PMID 34717533, 2021). "Additionally, we proved that JA/SA-related genes (LOX3, AOC4, COI1, PAL1, ICS1, NPR1) played important roles at the transcription level using the FPKM values from RNA-seq and relative transcript abundance from qRT-PCR in response to infection." (PMID 33446096, 2021). "PHS treatment significantly elevated mRNA levels of PR‐1a, PR‐3, PR‐4b, PR 5 (OSM), and SAR 8.2 at 48 h, as well as PR 5 and nonexpressor of PR1 (NPR1) at 72 h in pathogen‐infected tobacco plants compared with that in pathogen infection alone plants." (PMID 34622122, 2021). "For example, since NPR1 transcription is not dramatically up-regulated in response to plant pathogen infections, post-translational modifications of NPR1 regulate its localization, turnover, and functions in plant immunity." (PMID 32865553, 2020). "Their transcriptional induction in response to infection by (hemi)biotrophic pathogens or SA requires the coactivator NON-EXPRESSOR OF PATHOGENESIS-RELATED GENES 1 (NPR1)." (PMID 32218796, 2020). "Nonetheless, these results support the role of EXO70H4, NPR1, and ICS1 in the control of persistence of human pathogens in leaves at the pre- and/or post-invasion stage of infection, and suggest that the plant defense mediated by these proteins involves callose production." (PMID 31914927, 2020). "At 1 d.p.i of AvrRpt2 infection, rps2 and atg4a4b had no obvious plaques, while the leaves of npr1 and atg8a (ATG8a deletion mutant) shrunk." (PMID 32708160, 2020). "However, after infection, when SA levels increase, NPR4-NPR1 interaction is disrupted, allowing the accumulation of NPR1." (PMID 31057566, 2019). "NPR1 is essential for fighting off infections and plants that do not have this protein are highly susceptible to disease." (PMID 31589140, 2019). "NPR1 may be degraded by NPR3 or NPR4 under stress, with suppression of programmed cell death during ETI at an infection site." (PMID 30857376, 2019).
infection (continued). "NPR1 is constitutively expressed in many plants and is activated by modification after infection rather than at the transcriptional level." (PMID 31108845, 2019). "Upon pathogen infection or treatment with SA or its functional analogs 2,6-dichloroisonicotinic acid (INA) and benzothiadiazole (BTH), NPR1 translocates from the cytoplasm into the nucleus, where it interacts with the TGA2 transcription factor to promote expression of multiple PR genes." (PMID 30386355, 2018). "However, we found that the EDS1 gene was downregulated and the PAD4 and NPR1 genes upregulated, indicating differential regulation of EDS1, NPR1 and PAD4 gene expression during ToLCPalV infection." (PMID 29352245, 2018). "A slight decrease in resistance, e.g., trailing necrosis, was also observed upon infection of NahG and nonexpresser of pr genes 1 (npr1) plants after inoculation with an incompatible strain of P. brassicae." (PMID 28320402, 2017). "The 5′AlaCGC tRF mediated cleavage was experimentally mapped at the tRF binding sites on the mRNA targets of Non-expresser of pathogenesis related protein (NPR1), which was down-regulated during pathogen infection." (PMID 27313593, 2016). "Unlike its positive roles in SAR and ISR, the role that NPR1 plays in local tissue is harder to tease apart due to the entangled interplay between pathogen effectors and the host immune responses at the infection site." (PMID 27513560, 2016). "Upon pathogen infection or accumulation of SA, changes in cellular redox potential lead to the reduction of cysteines through the activity of thioredoxins (TRX-h3 and TRX-h5) and release of NPR1 monomers to localize to the nucleus." (PMID 27513560, 2016). "Pathogen infection significantly increased the SA-dependent gene NPR1 regardless of the invader type; moreover, pathogen infection induced significantly higher NPR1 transcripts under elevated [CO2] than under ambient [CO2]." (PMID 25657213, 2015). "NPR1 expression occurs at a low constitutive level and does not change dramatically upon SA induction or pathogen infection." (PMID 25873923, 2015). "As a negative control, their expression levels in sid2 and npr1 mutants after PstDC3000 infection were not altered compared with those in wild type." (PMID 26394921, 2015). "NPR1 overexpression in Arabidopsis did not trigger defense reactions until subsequent induction by chemicals or pathogen infection." (PMID 25431577, 2014). "Also, during Pst DC3000 infection, YSL3 was positively regulated by SA signaling through NPR1 and the upregulation was enhanced in the coi1 mutant that defective in the jasmonic acid (JA) receptor, CORONATINE INSENSITIVE1." (PMID 24845074, 2014). "The non-expressor of PR gene 1 (NPR1) is up-regulated by SA accumulation during pathogen infection and is routinely used as a marker gene to track SA-mediated signaling pathways." (PMID 25547733, 2014). "Using the protocol described, we have performed a genetic screen for suppressors of the npr1 (nonexpressor of pathogenesis-related genes) mutant that hyperaccumulates SA during pathogen infection." (PMID 20863393, 2010). "Based on these findings, we hypothesize that NPR1 (CCA0526S0240) in the early and mid-infection stages of American hickory may trigger early defense mechanisms through the SA-dependent pathway, improving the plant’s ability to recognize and respond to pathogens." (PMID 40094748, 2025). "However, the mechanism by which ATG6 suppresses pathogen infection by regulating NPR1 has not yet been reported." (PMID 40036061, 2025). "NPR1 plays a vital role in the salicylic acid (SA)-mediated systemic acquired resistance (SAR) pathway; in the establishment and control of systemic acquired resistance (SAR) as well as induced systemic resistance (ISR) which can restrict the spread of virulent pathogen infections in plants." (PMID 39161600, 2024).
infection (continued). "However, samples obtained through infection in an A. thaliana mutant lacking the SA receptor npr1 had differentially downregulated Osmotic Stress iModulon activity in comparison to all other AvrRpt2-induced ETI samples, where the iModulon was upregulated." (PMID 37638727, 2023). "However, when the authors controlled NPR1 expression, it resulted in increased accumulation of NPR1 upon pathogen infection, enhancing resistance to bacterial blight without negatively affecting plant growth and grain yield." (PMID 37106801, 2023). "Additionally, the expression of SA synthetic-related genes phenylalanine ammonia lyase (PAL) and the non-expressor of pathogenesis-related genes 1 (NPR1) were observed to be increased, indicating the possible increasement of SA content after infection." (PMID 35432404, 2022). "After inoculation with P. pannosa, the expression levels of NPR1, EDS1, SAG101, PR1, PR5, CAT, chorismate mutase, and PAL increased rapidly, resulting in the rapid synthesis of SA and increasing the acquired resistance of the plant at the early stages of pathogen infection." (PMID 35741765, 2022). "In the absence of infection, NPR1 is predominantly oligomeric and partitioned to the cytoplasm." (PMID 29581883, 2018). "Similarly, the interplay between SA, NPR1, and NPR3/4 fine-tunes NPR1 homeostasis in a SA concentration-dependent manner, which determines the levels and types of plant defense responses during pathogen infection." (PMID 27303403, 2016). "Therefore, we speculated that PpCAD1 might not directly regulate the defense response, supported by the no significant changes of defense genes PR10 and NPR1 in three genotypes after pathogen infection." (PMID 36344936, 2022). "However, neither mock-induced exudates (MEX) nor PEXs from npr1 and sid2 mutants could reduce bacterial growth in the recipient WT leaves after subsequent PsmES4326 infection." (PMID 36523630, 2022). "Therefore, in plants, NPR1 can interact with TCP proteins to regulate ICS1 transcription to promote SA accumulation or act downstream gene expression, facilitating plant response to pathogen infection partially due to NPR1 and TGA protein interaction to promote defense-related expression." (PMID 35668804, 2022). "Thus, it is reasonable to assume that in presence of SA, NPR1 regulates the activation of YSLs and the metal homeostasis function of YSL genes may induce ROS mediated HR and defense-related genes to establish plant immunity during pathogen infection." (PMID 33287151, 2020). "In addition, transcriptional level of NPR1 is not changed upon pathogen infection." (PMID 30444888, 2018). "In contrast, BPMV infection decreased the expression of ICS1 and NPR1, and PAD4 was not affected by either infection." (PMID 37099452, 2023). "The expression levels of PR1, NPR1, WRKY70, and FRK1 did not consistently differ among WT and mutant plants before subsequent pathogen infection, although they were sometimes higher in mutant vs. WT plants." (PMID 34194459, 2021). "Highlighting its NPR1-independent transcriptional induction, WRKY70 was similarly induced in WT and sdg8-1 upon infection despite the lack of induction of NPR1." (PMID 32218796, 2020). "(b) After pathogen attack, low SA levels in cells distant from the infection site block NPR4‐directed NPR1 destruction, leading to NPR1‐stimulated SAR but not HR." (PMID 31245748, 2018). "Overexpression of Arabidopsis NPR1 (AtNPR1) transcript in wheat conferred heritable resistance to FHB disease spread, but not initial infection." (PMID 24561479, 2014). "However, with the VRS application, none of NPR1, PIN2, and PR1b responded to RS infection, which implied that VRS inhibition of RS involved an intricate mechanism that required further research." (PMID 32204419, 2020).
infection (continued). "In Arabidopsis, the salicylic acid (SA)-dependent responses, activated upon pathogen infection, are mediated by the redox-regulated nuclear translocation of NON-EXPRESSOR OF PATHOGENESIS-RELATED GENES 1 (NPR1) and by an altered interaction between NPR1 and TGA1 and TGA2 TFs." (PMID 31428113, 2019). "Interestingly, the dufulin-treated plants exhibited similar NPR1 expression levels in both the healthy and TYLCV-infected plants by the end of the observation period, suggesting that dufulin strongly activates the SA pathway, irrespective of the infection status." (PMID 39861842, 2024). "However, NPR1 and ICS1 were not up-regulated significantly in cabbage at the early stage of infection, suggesting that SA signaling pathway-related genes might be involved in resistance at the later stage of infection." (PMID 36012543, 2022).
tumor (23 papers, 2011 to 2025). "NPR-1 is overexpressed in the tumor vasculature and in variety of tumor cells, including peritoneal tumor cells, in vitro and in vivo." (PMID 29772690, 2018). "With this approach, we can specifically destroy vessels surrounding the tumour by laser ablation and inhibit neovascularisation through NPR-1 blockage." (PMID 29162137, 2017). "In order to characterize the in vivo tumor response post-PDT on U87 xenografted nude rats and to understand how NPR-1 targeting could improve treatment efficiency, we performed MRI analysis and DWI (diffusion-weighted imaging) acquisitions." (PMID 36986856, 2023).
cancer (14 papers, 2011 to 2025). A tumor composed of atypical neoplastic, often pleomorphic cells that invade other tissues. "Additionally, NPR1’s role as a co-receptor for TGF-β1 facilitates cell proliferation and metastasis, further implicating NRP1 in cancer development and spread." (PMID 39334861, 2024).
bacterial infection (11 papers, 2010 to 2024). "As previously reported, we found npr1 mutants are more susceptible to bacterial infection than controls, albeit with a relatively low statistical significance in our experiments." (PMID 34659282, 2021). "As previously reported, npr1, nahG, and ics1/sid2 lines were more susceptible to bacterial infections." (PMID 31245710, 2018). "The isolate from Germany (strain RC301) carries the allele for NPR-1 215F, which is responsible for altered behavioral responses to food, oxygen, and other animals, as well as reduced immune responses to bacterial infections." (PMID 28179390, 2017). "Another phenotype of the Arabidopsis npr1 mutation is increased pathogen growth after bacterial infection of leaves." (PMID 21078185, 2010). "It is well known that Arabidopsis NPR1 increase defense responsive genes such as pathogenesis-related proteins through interaction with TGA and WRKY transcription factors to enhance bacterial disease resistance caused by Pseudomonas syringae." (PMID 30444888, 2018). "As a negative control for the bacterial infection experiment, a mutant with enhanced disease susceptibility, nonexpresser of pathogenesis-related genes 1 (npr1), was included." (PMID 39116132, 2024). "This was also observed in barley, in which overexpression of a conserved protein from the stripe rust pathogen that competes with TGA transcription factors for the binding with NPR1, reduced the induction of several PR genes in a leaf region adjacent to a bacterial infection." (PMID 29614079, 2018). "In fact, the expression of NPR1, ERF1 and EIN were downregulated because of the bacterial infection at this stage." (PMID 32887438, 2020).
cardiovascular disease (6 papers, 2012 to 2025). "The studies detailing the Npr1 (coding for NPRA) gene-disruption in mice have revealed the functional significance of NPRA in the control of blood pressure and cardiovascular disease states." (PMID 25202235, 2014). "Moreover, Npr1 gene-disruption activates NF-κB and AP-1, leading to cardiovascular disease conditions." (PMID 31416126, 2019).
neurological disorders (2 papers, 2021 to 2022). "Advances in this field have provided tremendous insights into the critical role of Npr1 (encoding GC-A/NPRA) in the reduction of fluid volume and blood pressure homeostasis, protection against renal and cardiac remodeling, and moderation and mediation of neurological disorders." (PMID 36683859, 2022).
NPR1 also shares sentences with these, for which no sentence is quoted: lung carcinoma (7 papers); essential hypertension (4); asthma (3); left ventricular hypertrophy (3); melanoma (3); Myocardial fibrosis (3); allergic asthma (2); eosinophilia (2); esophageal cancer (2); heart disease (2); kidney disease (2); Polyuria (2); prostate adenocarcinoma (2); small cell lung carcinoma (2); Stroke (2); tongue squamous cell carcinoma (2); acute kidney injury (1); adenocarcinoma (1); allergic disease (1); Aortic dissection (1); Arrhythmia (1); Ascites (1); aspergillosis (1); atrial fibrillation (1); benign prostatic hyperplasia (1); blood pressure (1); cervical cancer (1); chronic lung disease (1); colorectal cancer (1); depression (1).
A further 27 diseases each share a sentence with NPR1 in 1 paper.